OXSM (3-oxoacyl-ACP synthase, mitochondrial)
Description:
May play a role in the biosynthesis of lipoic acid as well as longer chain fatty acids required for optimal mitochondrial function.
Synonyms: KS; FLJ20604; FASN2D; CEM1; KASI
Tractability: Small molecule: a structure with a bound ligand is known; it has a high-quality binding pocket. PROTAC: ubiquitination databases record sites on it; its protein half-life has been measured.
Gene: Protein-coding gene on chromosome 3 (25,782,917 to 25,796,834, forward strand). Ensembl gene ENSG00000151093.
Subcellular location: Mitochondrion
Subcellular location (Human Protein Atlas): Cytosol; Mitochondria
Pathways (Reactome):
Metabolism of proteins: Mitochondrial protein degradation
Gene Ontology:
Molecular function: 3-oxoacyl-[acyl-carrier-protein] synthase activity; acyltransferase activity; acyltransferase activity, transferring groups other than amino-acyl groups
Biological process: acyl-CoA metabolic process; medium-chain fatty acid biosynthetic process; short-chain fatty acid biosynthetic process; fatty acid biosynthetic process; monocarboxylic acid metabolic process
Cellular component: mitochondrion; mitochondrial matrix
Genetic constraint (gnomAD): Loss-of-function variants: 19 observed, 29.16 expected, observed/expected ratio (o/e) 0.65, 90% interval 0.45 to 0.96. The upper end of that interval is the gene's LOEUF score, 0.96, which puts it in group 4 of 6, group 1 being the genes least tolerant of losing a copy. Missense variants: 550 observed, 576.79 expected, observed/expected ratio (o/e) 0.95, 90% interval 0.89 to 1.02. Synonymous variants: 177 observed, 205.92 expected, observed/expected ratio (o/e) 0.86, 90% interval 0.76 to 0.97.
Homologues: Orthologues: chimpanzee OXSM (99% identical), macaque OXSM (98% identical), dog OXSM (92% identical), guinea pig OXSM (91% identical), pig OXSM (91% identical), rabbit OXSM (88% identical), rat Oxsm (85% identical), mouse Oxsm (85% identical), tropical clawed frog oxsm (69% identical), zebrafish oxsm (65% identical), Drosophila melanogaster CG12170 (50% identical), Caenorhabditis elegans F10G8.9 (37% identical). Paralogues in human: FASN (22% identical).
Diseases named in the same sentence as OXSM in open-access papers:
OXSM is named in the same sentence as 16 diseases in open-access papers, as found by Europe PMC text mining. Sharing a sentence is not in itself a finding about the gene and the disease. The quoted sentences say what the papers report.
glioma (4 papers, 2023 to 2025). A benign or malignant brain and spinal cord tumor that arises from glial cells (astrocytes, oligodendrocytes, ependymal cells). "In our evaluation of the risk factors of eight genes, we identified SLC3A2, RPN1, NDUFA11, GYS1 and OXSM as potential risk factors for glioma prognosis." (PMID 38022537, 2023). "The forest map shows that these five genes (SLC3A2, RPN1, NDUFA11, GYS1, OXSM) might be high-risk factors for glioma prognosis." (PMID 38022537, 2023). "GYS1, NDUFA11, OXSM, RPN1, and SLC3A2 play a role in promoting cancer in glioma, while LRPPRC, NCKAP1, NDUFS1, NUBPL and SLC7A11 play a role in inhibiting tumour." (PMID 39993959, 2025).
bladder cancer (1 paper, 2024). "For instance, in bladder cancer (BLCA), OXSM was a risk factor for DFS and a protective factor for OS, DSS, and PFS." (PMID 38420162, 2024).
bladder urothelial carcinoma (1 paper, 2024). "In addition, a group of disulfidptosis-related genes (GYS1, LRPPRC, NDUFA11, OXSM, RPN1, SLC3A2, and SLC7A1) are found to influence the prognosis of bladder urothelial carcinoma via immune cell infiltration." (PMID 39701955, 2024).
endothelial dysfunction (1 paper, 2025). In vascular diseases, endothelial dysfunction is a systemic pathological state of the endothelium (the inner lining of blood vessels) and can be broadly defined as an imbalance between vasodilating and vasoconstricting substances produced by (or acting on) the endothelium. "The up-regulation of OXSM and MECR levels disrupts the “synthesis-degradation” balance of fatty acids, while Edu improves endothelial dysfunction, inhibits vascular wall inflammation and maintains vascular structural homeostasis by restoring this balance." (PMID 41614751, 2025).
oral squamous cell carcinomas (1 paper, 2023). "Enhancers at the OXSM locus have been identified as metastasis-specific enhancers in metastatic oral squamous cell carcinomas (OSCC), with OXSM playing a role in proliferation, invasion, and lipid synthesis in metastatic OSCC cells." (PMID 37427103, 2023).
ovarian carcinoma (1 paper, 2023). A malignant neoplasm originating from the surface ovarian epithelium. "To investigate the effect of OXSM on ovarian cancer cell proliferation and migration, we performed knockdown on the OXSM gene and overexpressed OXSM using an OXSM overexpression plasmid, respectively." (PMID 37087461, 2023). "Collectively, these findings showed that HSPD1 knockdown could inhibit the LA synthesis mediated by OXSM, which led to promotion of ovarian cancer cell proliferation." (PMID 37087461, 2023). "However, the role of OXSM in ovarian cancer needs further exploration." (PMID 37087461, 2023).
prostate carcinoma (1 paper, 2025). A carcinoma that arises from epithelial cells of the prostate gland. "Building on our previous research, further analysis of tumor progression within the training set revealed that RPN1 may act as a suppressor of prostate cancer progression, while OXSM, NDUFA11, and SLC7A11 appear to promote disease progression." (PMID 41330917, 2025). "Among them, SLC7A11, OXSM, RPN1, and NDUFA11 showed higher expression levels in prostate cancer tissues compared to normal samples." (PMID 41330917, 2025).
tumor (10 papers, 2023 to 2025). "Consistent with the potential tumor suppressive effect of OXSM in OC, LA exhibits a growth inhibitory effect and induces apoptosis in ovarian cell lines." (PMID 37087461, 2023). "Among tumor types, UCEC was found to present the most widespread somatic mutations of the disulfidptosis genes, such as SLC7A11 (92 %), NCKAP1 (85 %), LRPPRC (75 %), and OXSM (75 %)." (PMID 39605832, 2024). "Specifically, an elevation in the expression levels of PRN1, OXSM, SLC3A2, and CD2AP were observed in tumor tissues, while the expression levels of DSTN, FLNA, TLN1, IQGAP1, MYL6, NCKAP1, and NDUFS1 declined in tumor tissues." (PMID 39995998, 2025). "We analyzed the expression of genes in tumor and normal samples, and the results showed that NDUFS1, NDUFS2, NDUFC1, and EPAS1 were downregulated in CRC, and SLC7A11, OXSM, LRPPRC, NDIFA11, NUBPL, and CONT1 were upregulated in CRC." (PMID 37978247, 2023). "We compared the gene expression levels between normal and tumor tissues of COAD patients from TCGA and found that OXSM was significantly downregulated (p = 5.20 × 10–9), while TRIP6 (p = 5.00 × 10–12), MYH3 (p = 6.70 × 10–3), and MYH4 (p = 6.41 × 10–7) were upregulated in COAD tissues." (PMID 37524774, 2023).
cancer (7 papers, 2023 to 2025). A tumor composed of atypical neoplastic, often pleomorphic cells that invade other tissues. "The disulfidptosis genes: NCKAP1, LRPPRC, SLC7A11, OXSM, SLC3A2, NDUFS1, and GYS1 occurred somatic mutations in pan-cancer, with 1 % SNV frequency." (PMID 39605832, 2024). "Amplifications in genes such as SLC3A2, OXSM, and GYS1 were linked to increased expression in cancer tissues, whereas genes such as NDUFS1 and NCKAP1 showed reduced expression, underscoring the diverse impact of DRG expression on BLCA pathology." (PMID 38507521, 2024). "OXSM expression was positively associated with Putity (p = 1.81 × 10–2), B cells (p = 6.71 × 10–3) and CD8 + T Cells (p = 5.89 × 10–3).These results suggest that immune parameters can be used as potential biomarkers or therapeutic targets for cancer patients." (PMID 37524774, 2023). "Notably, RPN1, NUBPL, and OXSM demonstrate widespread CNV across various cancers." (PMID 38397869, 2024). "For instance, in most cancer types, the expression of SLC7A11, OXSM, and NDUFS1 was negatively correlated with methylation." (PMID 38397869, 2024). "We found that the expression of GYS1 and SLC7A11 were upregulated, while those of NCKAP1, NDUFS1, NUBPL, OXSM, RPN1, and SLC3A2 were downregulated in ccRCC tissues compared with those in the para-carcinoma tissues." (PMID 38271056, 2024). "Notably, NDUFA11, OXSM, LRPPRC, NCKAP1, RPN1, SLC3A2, and SLC7A11 were upregulated in cancer tissues, while NDUFS1 showed the opposite trend." (PMID 38213838, 2023).
OXSM also shares sentences with these, for which no sentence is quoted: brain tumor (1 paper); cardiac diseases (1); clear cell renal adenocarcinoma (1); fatty acid metabolism disorders (1); heart failure (1); prostate tumor (1); Wilson disease (1).